IL1B (interleukin 1 beta)
Diseases named in the same sentence as IL1B in open-access papers (continued):
Sharing a sentence is not in itself a finding about the gene and the disease.
osteoarthritis (continued). "The results showed that experimentally created osteoarthritis reduced the condylar cartilage thickness of rats and increased the gene expression of cytokines (IL-1β and TNFα) and positive cells of p65." (PMID 32083119, 2019). "In the osteoarthritis-like environment induced by IL-1β, the inhibition of pro-regenerative genes (i.e., SOX9, COL2A1 and ACAN) was observed, coinciding with the up-regulation of genes related to arthritic disease progression (i.e., ADAMTS4, PTGS2 and MMP13)." (PMID 30959772, 2019). "In the present study, we found that the accumulation of β-catenin and Wnt5a increased in IL-1β-induced osteoarthritis chondrocytes, and expression of the downstream transcription factor, RUNX2, was also increased." (PMID 31888697, 2019). "The levels of several inflammatory mediators, such as interleukin-1β (IL-1β) and tumor necrosis factor α (TNFα), are augmented in the joint tissue of osteoarthritis patients." (PMID 31905764, 2019). "Our results from an in-vitro model of osteoarthritis indicate that genistein inhibits the IL-1β-induced expression of the catabolic factors nitric oxide synthase 2 (NOS2), cyclooxygenase 2 (COX-2), and matrix metalloproteinases (MMPs)." (PMID 31137797, 2019). "In particular, when EGCG is used in interleukin-1-beta (IL-1β)-stimulated human osteoarthritis chondrocytes cell line, it was able to upregulate and downregulate a plethora of miRNAs." (PMID 31878082, 2019). "High‐mobility group box 1 was negatively correlated with CCN3 in IL‐1β‐induced osteoarthritis responses, and HMGB1 is involved in the protective effect of CCN3 in OA." (PMID 31454155, 2019). "After careful review of the recent literature, results for vascular endothelial growth factor A (VEGFA) and interleukin 1 beta (IL1β) were diametrically opposite to those in our osteoarthritis microarray analysis, so we excluded them." (PMID 30560591, 2019). "Our data showed that HMGB1 was negatively correlated with CCN3 expression in IL‐1β‐induced osteoarthritis responses." (PMID 31454155, 2019). "With regard to OA, previous studies have reported that Ast reduces IL-1β-induced MMP expression in chondrocytes, and ameliorates cartilage loss in experimental osteoarthritis." (PMID 31772142, 2019). "In our previous research, the expression levels of IL6 and IL-1β were significantly increased in osteoarthritis synovial membranes." (PMID 31139654, 2019). "AMPK activation in osteoarthritis cartilage is decreased, and its inhibition enhances the catabolic responses to pro-inflammatory signals, such as IL-1β and TNFα." (PMID 31546898, 2019). "Primary rat articular chondrocytes were treated with IL-1β to mimic the early stage of osteoarthritis in vitro." (PMID 31404098, 2019). "Synovial inflammation mainly resulting from interleukin-1 beta (IL-1β) plays a crucial role in the early and late stage of osteoarthritis." (PMID 30276528, 2018). "ELF3 levels are elevated in human cartilage from patients with osteoarthritis (OA), and ELF3 contributes to the IL-1β-induced expression of genes encoding Mmp13, Nos2, and Ptgs2/Cox2 in chondrocytes in vitro." (PMID 29691435, 2018). "Since IL-1β plays an important role in the pathogenesis of osteoarthritis, it has often been used to establish an in vitro osteoarthritis model in chondrocytes." (PMID 29483929, 2018). "The level of miR-448 was significantly higher and matrilin-3 expression was significantly lower in osteoarthritis cartilage and IL-1β-induced chondrocytes than in normal tissues and cells." (PMID 29483929, 2018). "Previous reports also demonstrated that BA inhibited IL-1β-induced inflammation via activating PPARγ in osteoarthritis chondrocytes." (PMID 29666569, 2018). "Here, we examined the functional roles of miR-448 and its expression in osteoarthritis tissues, including IL-1β-stimulated osteoarthritis chondrocytes." (PMID 29483929, 2018).
osteoarthritis (continued). "A recent report has depicted that this bioactive component inhibited IL-1β-induced inflammation via downregulating NF-κB and MAPKs signaling in human osteoarthritis chondrocytes." (PMID 29370858, 2018). "This approach allowed us to obtain an osteoarthritis model that responds to IL-1β-induced inflammatory stimulus." (PMID 30960663, 2018). "Previous study reported the association of IL1RN with IL-1β in osteoarthritis, suggesting that the upregulation of IL1RN in σB transfected cell, can increase the occurrence of osteoarthritis." (PMID 29731966, 2018). "Our findings demonstrate that miR-448 inhibition directly upregulated matrilin-3 expression, protecting IL-1β-induced and osteoarthritis chondrocytes from ECM degradation." (PMID 29483929, 2018). "Our data show that the level of miR-448 was significantly higher in osteoarthritis cartilage than in normal cartilage, and significantly increased in response to IL-1β stimulation." (PMID 29483929, 2018). "Microarray analysis data of ARV infected cells and σB transfected cells were validated by using primers of 4 important candidate genes (SPP1, BMP2, SMAD1 and IL1B) that were involved in osteoarthritis pathway." (PMID 29731966, 2018). "Compared with the control group, the levels of phosphorylation of NF-κB p65 and IκBα increased significantly in IL-1β-stimulated human osteoarthritis chondrocytes." (PMID 29179489, 2017). "Osteoarthritis is a degenerative disease of articular chondrocytes and involves several inflammatory pathways and mediators such as IL-6, IL-1β and NO." (PMID 28355351, 2017). "We investigated the effects of SSa on IL-1β-induced NF-κB activation to test the anti-inflammatory mechanism of SSa in human osteoarthritis chondrocytes." (PMID 29179489, 2017). "Sesamin supplementation can have a synergistic effect on drugs for osteoarthritis treatment that target IL-1β production and processing." (PMID 28569157, 2017). "The IL-1β is a critical mediator of osteoarthritis and the intra-articular injection of this recombinant cytokine has been used to induce a transient inflammatory response in an experimentally induced synovitis." (PMID 28377922, 2017). "Chondrocytes were isolated, and 5 ng/mL of IL-1β was added to mimic the in vitro osteoarthritis (OA) model." (PMID 29333456, 2017). "Compared with the control group, the mRNA and protein levels of MMP1, MMP3, and MMP13 increased significantly in IL-1β-stimulated human osteoarthritis chondrocytes." (PMID 29179489, 2017). "The potential role of IL-1β as a link in pathogenesis for both gout and OA has been demonstrated in the Prediction of Osteoarthritis Progression study." (PMID 29326934, 2017). "Equine BMSCs express high levels of galectin-1 mRNA relative to other articular cell types; however, BMSC galectin mRNA expression is diminished in the presence of pro-inflammatory cytokines prevalent in osteoarthritis (IL-1β and TNF-α)." (PMID 29096716, 2017). "Cytokines, particularly Interleukin-1 beta (IL-1β), play a major role in the development and progression of osteoarthritis (OA)." (PMID 28744016, 2017). "Compared with the control group, the levels of NO and PGE2 increased significantly in IL-1β-stimulated human osteoarthritis chondrocytes." (PMID 29179489, 2017). "The results indicated that SSa inhibited IL-1β-induced inflammation in human osteoarthritis chondrocytes by activating LXRα." (PMID 29179489, 2017). "Nuclear translocation of p50 and p65 proteins in osteoarthritis (OA) fibroblast-like synoviocytes (FLS) in response to IL-1β stimulation in the absence or presence of rhPRG4 was studied using DNA binding assays." (PMID 28482921, 2017). "In osteoarthritis (OA), activated synoviocytes and articular chondrocytes produce pro-inflammatory cytokines, such as IL-1β, that promote chondrocyte apoptosis and activate the NF-κB signaling pathway to induce catabolic factors." (PMID 29207603, 2017).
osteoarthritis (continued). "Few studies have shown that IL-4 is associated with the pathological process of osteoarthritis; accordingly, we mainly explored the expression of IL-4 and the relationship between IL-4 and SOCS1 in IL-1β-stimulated human osteoarthritic chondrocytes." (PMID 28373981, 2017). "IL-1β treatment showed a modest effect on the expression profile of miRNAs in normal and osteoarthritis (OA) chondrocytes." (PMID 29123165, 2017). "In the present study, we investigated the anti-inflammatory effect of SSa on IL-1β-stimulated human osteoarthritis chondrocytes." (PMID 29179489, 2017). "In this study, we evaluated the anti-inflammatory effects of sesamin on IL-1β-stimulated human osteoarthritis chondrocytes and investigated the possible mechanism." (PMID 27863411, 2016). "It has also been proven to be a chondroprotective agent in the osteoarthritis model induced with IL-1β." (PMID 27400672, 2016). "Sesamin has shown the ability to protect against cartilage destruction in IL-1β-induced inflammation in the Osteoarthritis (OA) model, both in in vitro and in vivo studies." (PMID 27400672, 2016). "In the present study, we investigated the anti-inflammatory effect and mechanism of sesamin on IL-1β-stimulated human osteoarthritis chondrocytes." (PMID 27863411, 2016). "The migratory activity of articular CPC from patients with osteoarthritis was strongly inhibited by the pro-inflammatory cytokine IL-1β." (PMID 26877866, 2016). "Chondrocytes stimulated with IL-1β in vitro have been exploited to imitate the microenvironment that occurs in osteoarthritis (OA)." (PMID 26107568, 2015). "A rat model of osteoarthritis (OA) in vitro was established using 10 ng/ml IL-1β as modulating and chondrocytes inducing agent." (PMID 25888442, 2015). "It has been reported that TNFα and IL1β differently affect degenerative joint diseases such as osteoarthritis." (PMID 25157407, 2014). "It is known that pro-inflammatory cytokines, such as IL-1β and TNF-α, play a role in the pathogenesis of osteoarthritis; therefore, the present study established a model of OA using normal human articular cartilage cells stimulated by recombinant human IL-1β." (PMID 24348789, 2014). "Although additional research is needed to sustain such a claim, recent evidence demonstrated that the addition of WNT and BMP antagonist sclerostin was able to prevent an IL-1β-induced osteoarthritis-like phenotype." (PMID 24286177, 2013). "This study investigated the effect of Angelica sinensis polysaccharides (APS-3c) on rat osteoarthritis (OA) model in vivo and rat interleukin-1-beta- (IL-1β-) stimulated chondrocytes in vitro." (PMID 23861713, 2013). "What is more important, we found that MiR-194 was elevated in IL-1β induced osteoarthritis, and it is accompanied by decreased expression of Sox5." (PMID 22396742, 2012). "Interleukin-1β (IL-1β) is a pro-inflammatory cytokine that plays a key role in the pathogenesis of osteoarthritis (OA)." (PMID 22194879, 2011). "IL-1β is an inflammatory cytokine and its inhibition has been shown to ameliorate osteoarthritis-like pathology in animal models." (PMID 21682898, 2011). "We have recently reported that HMGB1 is released by osteoarthritic synoviocytes after activation with interleukin-1beta (IL-1β) The present study investigated the role of HMGB1 in synovial inflammation in osteoarthritis (OA)." (PMID 20799933, 2010). "p38-MAPK is a major signal-transducing pathway in osteoarthritis (OA) and its activation by interleukin-1β (IL-1β) plays a critical role in the expression and production of several mediators of cartilage catabolism in OA." (PMID 20955562, 2010). "In inflammatory joint disease, such as osteoarthritis (OA), there is an increased level of proinflammatory cytokines, such as interleukin (IL)-1β." (PMID 21059244, 2010).
osteoarthritis (continued). "This is in agreement with an animal study that reported an increase in markers of osteoarthritis in dogs with acetabular dysplasia (including IL-1β, IL-6, tumor necrosis factor (TNF)-alpha, and matrix metalloproteinase (MMP)-3) in comparison to normal dogs." (PMID 20367415, 2010). "Human chondrocytes and hPSCs isolated from cartilages and synovium of Osteoarthritis (OA) patients were cultured with 10% fetal bovine serum media or serum free media before treatment with IL-1β, TGF-β1, or Connective tissue growth factor (CTGF)." (PMID 19852794, 2009). "Proinflammatory cytokines such as TNF-α and IL-1β have been shown to mediate cartilage degradation and apoptosis in chondrocytes in degenerative joint diseases such as RA and OA in humans as well as in animals." (PMID 19889203, 2009). "Two polymorphisms within Interleukin-1β Gene (IL1β) and one within the IL-1 receptor (IL1RN) were chosen for haplotype association with the occurrence of radiographic osteoarthritis (ROA) in the hip, knee and hand." (PMID 19751505, 2009). "IL-1β was found to induce a distinct response in chondrosarcoma obtained from osteoarthritis chondrocytes." (PMID 20034400, 2009). "The aims of this study were to investigate the expressions of H-PGDS and L-PGDS in cartilage from healthy donors and from patients with osteoarthritis (OA) and to characterize their regulation by interleukin-1-beta (IL-1β) in cultured OA chondrocytes." (PMID 19094210, 2008). "In vitro evaluations confirmed that CDs-3/siIhh could efficiently regulate the Indian Hedgehog (Ihh) signaling pathway and osteoarthritis (OA)-related markers in both normal and IL-1β-induced inflammatory ATDC5 chondrocytes." (PMID 41677519, 2026). "Furthermore, additional studies have revealed that SS-a can increase the reduction in the p-IkB/β-actin ratio from 30.00% to 81.00% and enhance the increase in LXRα expression from 137.50% to 525.00% in human osteoarthritis chondrocytes stimulated by IL-1β." (PMID 41011202, 2025). "Liensinine also suppresses IL-1β-induced chondrocyte inflammation via NF-κB inhibition and improves cartilage damage in osteoarthritis models, indicating its potential utility in osteoarthritis treatment." (PMID 41154606, 2025). "We hypothesized that the knockdown of TRPV3 may mitigate the effects induced by IL-1β in patients with osteoarthritis." (PMID 40166423, 2025). "Similarly, MSC-derived supernatants modulate senescence in IL1β-treated osteoarthritis chondrocytes by regulating SA-β-Gal and reducing γH2AX foci and actin stress fibers." (PMID 40465768, 2025). "Besides, STM alleviates injuries of rat articular chondrocytes in osteoarthritis by negating IL-1β-induced inflammation." (PMID 40226364, 2025). "Subsequently, to investigate EGCG’s effects on chondrocytes under osteoarthritis (OA)-mimicking conditions, cells were stimulated with IL-1β (10 ng/mL) for 24 h to establish the disease model group (Model), followed by treatment with 10 μg/mL EGCG for an additional 24 h (EGCG group)." (PMID 40880649, 2025). "Similarly, in MIA-induced osteoarthritis rat models, Rb1 (10 mg/kg) administration for 2 weeks improved joint histology, suppressed pro-inflammatory cytokines (e.g., IL-1β and IL-6), and enhanced chondrocyte viability." (PMID 40507179, 2025). "Specifically, increased miR-145a-5p may slow the progression of osteoarthritis by inhibiting the function of inflammatory factors, such as IL-1β." (PMID 40860660, 2025). "Moreover, as an anti-inflammatory agent, betulinic acid has been shown to inhibit IL-1β-induced inflammation in human osteoarthritis chondrocytes, an effect that can be reversed by GW9662, a potent synthetic PPARG antagonist." (PMID 40564064, 2025). "Consequently, investigating specific processes related to IL-1β induced chondrocyte apoptosis and inflammation is crucial for advancing targeted treatments for osteoarthritis." (PMID 40166423, 2025).
osteoarthritis (continued). "However, no studies to date have specifically examined the effects of MOP on interleukin-1β (IL-1β)-stimulated chondrocyte inflammation or the progression of osteoarthritis (OA)." (PMID 39819383, 2025). "Additionally, miR-92a-3p downregulated the expression of ADAMTS-4/5 induced by IL-1β in chondrogenic hMSCs and human chondrocytes, thereby inhibiting the progression of osteoarthritis." (PMID 38816719, 2024). "Mechanistically, m6A modification up-regulates the expression of LINC00680 in the osteoarthritis tissue and interleukin-1β (IL-1β)-induced isolated primary chondrocytes, and the latter enhances the mRNA stability of SIRT1, a gene with definite functions in osteoarthritis." (PMID 38665846, 2024). "Pro-inflammatory cytokines such as IL-1β, TNF-α, and IL-6, which are key compounds in the pathogenesis of osteoarthritis, may lead to the loss of articular cartilage homeostasis through metabolic changes and significantly accelerate joint injury." (PMID 37548663, 2024). "IL-1β, central to the inflammatory response in osteoarthritis, elevates the expression of MMPs in chondrocytes, and an increase in MMPs due to elevated IL-1β is identified as one of the primary mechanisms of osteoarthritis." (PMID 38542192, 2024). "Retinoic acid also prevents inflammation by inhibiting TNF-α and IL-1β in osteoarthritis models." (PMID 38527023, 2024). "Research has shown that golden buckwheat extract could delay the development of inflammation in rats with osteoarthritis of the knee by inhibiting the production of IL‐1β, TNFα, and IL‐6." (PMID 39139945, 2024). "In patients with osteoarthritis without any clinical signs of gout, researchers found that uric acid levels in the synovial fluid were associated with IL-18, IL-1β, and radiographic severity of OA." (PMID 39775222, 2024). "In addition, both cell lines can produce the three main pro-inflammatory cytokines that are significantly elevated in osteoarthritis patients, namely, IL-1β, IL-6, and TNF-α." (PMID 39204123, 2024). "However, in conditions like osteoarthritis, the synovial fluid also contains a diverse range of compounds implicated in inflammation and catabolism, such as IL6, IFNγ, MMPs, TNFα and IL-1β." (PMID 39126115, 2024). "Minocycline might be considered as an anti-IL-1β therapeutic supplement in the treatment of osteoarthritis." (PMID 38487083, 2024). "In the present study, chondrocytes stimulated with IL-1β exhibited downregulation of COL2A1 and upregulation of MMP13, Prg4, Sulf1, Adam10, and Fstl1, supporting that enhanced inflammation is a critical mechanism underlying the progression of osteoarthritis." (PMID 37525533, 2023). "Stimulation with IL-1β increased oxidative stress, enhanced autophagy, and induced cell apoptosis, confirming that these biological processes are involved in the development of osteoarthritis." (PMID 37525533, 2023). "Similarly, our study showed that RUNX2 is highly expressed in patients with osteoarthritis, as well as mouse primary chondrocytes stimulated by IL-1β also upregulates RUNX2." (PMID 36915153, 2023). "In addition, lncRNA SNHG7 attenuated miR-214-5p-mediated PPARGC1B pathway and led to inhibition of IL-1β-induced osteoarthritis via suppression of NLRP3 inflammasome and apoptosis." (PMID 37779916, 2023). "USP14 was highly elevated in osteoarthritis articular cartilage and IL-1β-induced chondrocytes." (PMID 37359559, 2023). "A recent study implies that omentin-1 could have clinical relevance in the treatment of osteoarthritis by inhibiting IL-1β-induced chondrocyte senescence." (PMID 36632467, 2023). "TNF-α, like IL-1β, is considered an essential inflammatory factor associated with the development of KOA, and plays a pivotal role in the degradation of cartilage matrix and bone destruction in osteoarthritis." (PMID 37718444, 2023). "At present, IL-1β is usually used to induce osteoarthritis models in chondrocytes." (PMID 37953787, 2023).